AMIGO2 (adhesion molecule with Ig like domain 2)
Description:
Required for depolarization-dependent survival of cultured cerebellar granule neurons. May mediate homophilic as well as heterophilic cell-cell interaction with AMIGO1 or AMIGO3. May contribute to signal transduction through its intracellular domain. May be required for tumorigenesis of a subset of gastric adenocarcinomas.
Synonyms: DEGA; ALI1; AMIGO-2
Tractability: Antibody: UniProt places it where antibodies can reach, with medium confidence; UniProt predicts a signal peptide or a membrane-spanning region; its Gene Ontology location is reachable by antibodies, with medium confidence; the Human Protein Atlas places it where antibodies can reach. PROTAC: ubiquitination databases record sites on it.
Gene: Protein-coding gene on chromosome 12 (47,075,707 to 47,080,902, reverse strand). Ensembl gene ENSG00000139211.
Subcellular location: Cell membrane; Nucleus
Subcellular location (Human Protein Atlas): Golgi apparatus; Plasma membrane; Cytosol
Pathways (Reactome):
Signal Transduction: RAC1 GTPase cycle; RAC3 GTPase cycle
Gene Ontology:
Molecular function: protein binding
Biological process: brain development; heterophilic cell-cell adhesion; homophilic cell-cell adhesion; negative regulation of programmed cell death; positive regulation of synapse assembly
Cellular component: membrane; nucleus; plasma membrane
Genetic constraint (gnomAD): Loss-of-function variants: 18 observed, 27.51 expected, observed/expected ratio (o/e) 0.65, 90% interval 0.45 to 0.97. The upper end of that interval is the gene's LOEUF score, 0.97, which puts it in group 4 of 6, group 1 being the genes least tolerant of losing a copy. Missense variants: 561 observed, 674.21 expected, observed/expected ratio (o/e) 0.83, 90% interval 0.78 to 0.89. Synonymous variants: 264 observed, 269.35 expected, observed/expected ratio (o/e) 0.98, 90% interval 0.89 to 1.09.
Homologues: Orthologues: chimpanzee AMIGO2 (100% identical), macaque AMIGO2 (99% identical), guinea pig AMIGO2 (93% identical), dog AMIGO2 (91% identical), pig AMIGO2 (90% identical), mouse Amigo2 (88% identical), rat Amigo2 (86% identical), tropical clawed frog amigo2 (61% identical). Paralogues in human: AMIGO1 (39% identical), AMIGO3 (32% identical).
Diseases named in the same sentence as AMIGO2 in open-access papers:
AMIGO2 is named in the same sentence as 34 diseases in open-access papers, as found by Europe PMC text mining. Sharing a sentence is not in itself a finding about the gene and the disease. The quoted sentences say what the papers report.
gastric adenocarcinoma (9 papers, 2015 to 2024). "Among other genes, AMIGO2 and PHKG2 are associated with gastric adenocarcinoma and glycogen storage disease, respectively." (PMID 38764094, 2024). "Some studies have shown that MATN3 and AMIGO2 are overexpressed in gastric adenocarcinoma and can serve as markers of poor prognosis." (PMID 35719914, 2022). "It has been reported that in ECs and in gastric adenocarcinoma cell lines the inhibition of AMIGO2 affected the ability to adhere to extracellular matrix components." (PMID 35711359, 2022). "AMIGO2 mRNA was found to be differentially expressed in near half of cancer vs. normal tissue from gastric adenocarcinoma patients." (PMID 29182684, 2017). "AMIGO2 (Adhesion Molecule With Ig Like Domain 2) also named as DEGA (Differentially expressed in gastric adenocarcinomas)." (PMID 28611293, 2017). "AMIGO2 has been shown to be differentially expressed in other cancers including gastric adenocarcinomas, and it is known to effect ploidy, chromosomal stability, cell adhesion/migration, and tumourigenicity." (PMID 27671774, 2016). "In the gastric adenocarcinoma cell line, AMIGO2 was reported to be involved in cell adhesion, extracellular matrix, and basement membrane formation." (PMID 26357653, 2015). "AMIGO2 (Adhesion Molecule with Ig Like Domain 2), also called DEGA (Differentially Expressed in Gastric Adenocarcinoma) was found to play a potential role in carcinogenesis in 2004." (PMID 38189855, 2024).
melanoma (8 papers, 2018 to 2026). A malignant, usually aggressive tumor composed of atypical, neoplastic melanocytes. "In contrast, the top SFPQ-enriched mRNA transcripts in melanoma cells were generally associated with disease progression, such as AMIGO2, MAGEA3, MAGEA1, and the transcription factor, SOX10." (PMID 34218270, 2021). "The association between organ carcinogenesis and AMIGO2 expression has been reported in various types of cancer, including gastric cancer, pancreatic cancer, colorectal cancer, breast cancer, ovarian cancer, endometrial cancer, melanoma, and pituitary neuroendocrine tumors." (PMID 35094710, 2022). "To date, there have been only four reports of AMIGO2 immunostaining in tumour tissues, human melanoma and our previous studies on colorectal and gastric cancers." (PMID 35296279, 2022). "AMIGO2 has been reported as a novel pathogenesis-related gene in gastric cancer, melanoma, ovarian cancer, and pituitary neuroendocrine tumors." (PMID 35094710, 2022). "The authors showed that AMIGO2 is regulated by a melanoma-specific BRD2/4-bound promoter and super-enhancer configuration." (PMID 32042336, 2020). "More recently, Amigo2 has been found to play a role in endothelial and melanoma cells, as Amigo2 regulates apoptosis." (PMID 29924804, 2018). "PTK7 is regulated by AMIGO2 to promote melanoma cell survival." (PMID 39474113, 2024). "AMIGO2 also can promote liver metastasis by regulating the tumor cell adhesion to liver endothelial cells and it function as a pro-proliferation factor in human melanoma in vitro and in vivo." (PMID 34760348, 2021). "Regarding the role played by PTK7 in melanoma, it has been shown that PTK7 is regulated by AMIGO2, and the two work together to promote tumor cell survival." (PMID 39474113, 2024). "Moreover, transcriptomic analysis of melanocytes and melanoma cells exposed to the BET inhibitor JQ1 identified the transmembrane protein, AMIGO2, as a BET target gene essential for melanoma cell survival." (PMID 32042336, 2020).
colorectal cancer (6 papers, 2014 to 2026). A primary or metastatic malignant neoplasm that affects the colon or rectum. "In fact, our histopathological study revealed a close association between AMIGO2 expression in primary tumors from patients with colorectal cancer and liver metastasis." (PMID 35039535, 2022). "In colorectal cancer (CRC), elevated AMIGO2 expression has been linked to liver metastasis and poor prognosis." (PMID 41583520, 2026). "Existing studies have shown that AMIGO2 serves as a novel marker for liver metastasis in colorectal cancer patients." (PMID 39596644, 2024). "Immunohistochemical analysis of AMIGO2 expression in colorectal cancer (CRC) using a commercially available anti-AMIGO2 mouse monoclonal antibody clone sc-373699 (sc mAb) correlated with liver metastasis and poor prognosis." (PMID 35094710, 2022). "Accordingly, our previous study showed that in human colorectal cancer, AMIGO2 expression was correlated with liver, but not lung or peritoneal, metastasis." (PMID 35296279, 2022). "Extrapolation of this phenomenon in human cancers has been reported by immunohistochemical staining of AMIGO2 expression in human colorectal cancer (CRC) tissue, which is closely associated with AMIGO2 expression and liver metastasis, but not with lung metastasis and peritoneal dissemination." (PMID 35094710, 2022). "We showed that AMIGO2-containing EVs derived from AMIGO2-expressing gastric cancer cells (MKN-28 A1 & A2) enhanced the adhesion of HHSECs to the same gastric cancer cells (MKN-28) as well as to different gastric cancer cells (MKN-74) and colorectal cancer cells (SW480)." (PMID 35039535, 2022). "When EV-derived AMIGO2 was internalized in HHSECs, it significantly enhanced the adhesion of HHSECs to gastric (MKN-28 and MKN-74) and colorectal cancer cells (SW480), all of which lacked AMIGO2 expression." (PMID 35039535, 2022).
gastric cancer (6 papers, 2017 to 2026). A primary or metastatic malignant neoplasm involving the stomach. "Down-regulation of the AMIGO2 limits proliferation, migration, and invasion in gastric cancer cell lines." (PMID 38189855, 2024). "Western blotting indicated that AMIGO2 was present in EVs from AMIGO2-overexpressing MKN-28 gastric cancer cells." (PMID 35039535, 2022). "To investigate the function of AMIGO2 in EVs derived from AMIGO2-overexpressing cancer cells, we established AMIGO2-overexpressing MKN-28 human gastric cancer cell lines (MKN-28 A1, A2) and control vector-transfected cell lines (MKN-28 E1, E2)." (PMID 35039535, 2022). "We found that Amigo2 was more strongly expressed at the surfaces of cells in liver metastatic lesions compared to its expression in primary lesions of human colon and gastric cancers." (PMID 28272394, 2017). "To determine if it was possible to extrapolate the results of the animal experiments to human cancers, we next analysed Amigo2 expression in clinically matched primary and liver metastatic colon and gastric cancers using immunohistochemistry." (PMID 28272394, 2017). "Amigo2 has been found to play a pathological role in tumour growth as well as in cell adhesion to, and migration through collagen of gastric cancer cells." (PMID 28272394, 2017). "Moreover, AMIGO2 has been shown to enhance the adhesiveness of liver endothelial cells in colorectal and gastric cancers, thereby facilitating liver metastasis 17, 18, 26-29." (PMID 41583520, 2026). "We found that AMIGO2, a liver metastasis driver molecule, was transferred from human gastric cancer cells to hepatic sinusoidal endothelial cells via tumor-derived EVs, and that the AMIGO2 delivered by EVs enhanced the adhesion of endothelial cells to cancer cells." (PMID 35039535, 2022). "Furthermore, transcriptionally high levels of AMIGO2 are associated with shortened survival of patients with CRC, breast cancer, and gastric cancer." (PMID 35094710, 2022).
breast carcinoma (4 papers, 2018 to 2024). "Four drug resistance genes (AMIGO2, LGALS3BP, SCUBE2 and WLS) were found to be promising tools for ER+ and HER2- breast cancer risk stratification." (PMID 34760348, 2021). "To gain insight into the role of Amigo2 in human breast cancer, we analyzed the relationship between Amigo2 levels in different breast cancer subtypes." (PMID 29924804, 2018). "Consistent with what we found for 4T1 cells, HCC1143 K14.tRFP+ populations had significantly higher levels of Amigo2 mRNA compared with the K14− population, demonstrating the relationship between K14 status and Amigo2 expression in human breast cancer cells." (PMID 29924804, 2018). "AMIGO2 also acts as a key promoter of malignant phenotype in breast cancer." (PMID 38189855, 2024). "In addition, we report the identification of Amigo2 as a new mediator of invasion in breast cancer." (PMID 29924804, 2018). "To determine if differential expression of Amigo2 is observed in other models of breast cancer, we used HCC1143, a human breast cancer cell line that is known to express both luminal and basal keratins." (PMID 29924804, 2018).
fibrosarcoma (3 papers, 2017 to 2022). A malignant mesenchymal fibroblastic neoplasm affecting the soft tissue and bone. "Up-regulation of AMIGO2 in fibrosarcoma cells promoted liver metastasis through the development of liver endothelial cell adhesion." (PMID 29340021, 2017). "By using these liver-metastatic cells, we found for the first time that the Amigo2 gene is likely to play a central role in fibrosarcoma cell adhesion to liver endothelial cells as well as in the formation of metastatic foci in the liver." (PMID 28272394, 2017).
pancreatic cancer (3 papers, 2017 to 2026). "We identify AMIGO2 as a promising prognostic biomarker and therapeutic target, providing a foundation for improved diagnostic and precision-medicine strategies in pancreatic cancer." (PMID 41583520, 2026). "Silencing AMIGO2 led to specific increase in E-cadherin expression indicating partial inhibition of EMT in pancreatic cancer cells." (PMID 41583520, 2026). "Consistently, inhibition of AMIGO2 expression in pancreatic cancer cells reduced migration and invasion while restoring E-cadherin expression, indicating inhibition of epithelial mesenchymal transition." (PMID 41583520, 2026). "Together, these findings provide direct experimental evidence that AMIGO2 functions as an active driver of EMT-associated migration and invasion in pancreatic cancer cells, thereby reinforcing its central role in PAAD metastasis." (PMID 41583520, 2026). "Together, these findings demonstrate that AMIGO2 promotes PAAD aggressiveness by enhancing adhesion- and EMT-associated pathways, establishing it as a potential prognostic biomarker and therapeutic target in pancreatic cancer." (PMID 41583520, 2026). "Consistent with these bioinformatic findings, in vitro knockdown of AMIGO2 significantly impaired the migratory and invasive abilities of pancreatic cancer cells and upregulated E-cadherin expression, confirming its functional involvement in EMT and metastasis." (PMID 41583520, 2026). "Antibodies against AMIGO2 had been proved to be effective to pancreatic cancer in xenograft models." (PMID 28611293, 2017). "To experimentally validate these in silico findings, we next performed in vitro functional assays, which demonstrated that AMIGO2 plays an active functional role in promoting EMT and invasive behavior in pancreatic cancer cells." (PMID 41583520, 2026). "In addition, bioinformatics analysis using the transcriptome database selected AMIGO2 as a cancer-related gene candidate for CRC, pancreatic cancer, and endometrial cancer." (PMID 35094710, 2022). "We also identified novel pancreatic cancer genes, such as SCML2, COL17A1, AMIGO2, PTPRR, suggesting our method might be able to predict novel PDAC-related genes." (PMID 28611293, 2017).
bladder cancer (2 papers, 2024 to 2026). "PPAR-γ is overexpressed in bladder cancer cell lines T24 and 5637, but when AMIGO2 is knocked down in T24 and 5637, the expression level of PPAR-γ is also decreased." (PMID 38978149, 2024). "The relative mRNA expression of AMIGO2 in bladder cancer tissues was significantly higher than that of their matched adjacent normal tissues (n = 11)." (PMID 38978149, 2024). "As a consequence, it is identified that downregulating AMIGO2 inhibits bladder cancer cells proliferation and tumorigenicity by suppressing PPAR-γ, and that PPAR-γ is essential for AMIGO2-mediated cell proliferation in bladder cancer." (PMID 38978149, 2024). "This study aims to reveal the relationship between AMIGO2 and proliferation, migration and tumorigenicity of bladder cancer, and explore the potential molecular mechanisms." (PMID 38978149, 2024). "The protein expression level of AMIGO2 was also up-regulated in bladder cancer tissues compared with the matched adjacent normal tissues (n = 16)." (PMID 38978149, 2024). "Mechanistically, we identified the PPAR-γ as a principal molecular subject to modulation by AMIGO2 within bladder cancer cell populations." (PMID 38978149, 2024). "The result of qRT-PCR showed that the AMIGO2 expression level was elevated in bladder cancer cell lines T24 and 5636 compared with SV-HUC-1." (PMID 38978149, 2024). "In the present study, we found that AMIGO2 was upregulated in bladder cancer cells and tissues, and it could promote the proliferation, migration and tumorigenicity." (PMID 38978149, 2024). "In our study, we proved that overexpression of PPAR-γ in AMIGO2-repressed cells could revert the inhibitory effect of shAMIGO2 on bladder cancer cells." (PMID 38978149, 2024). "In the present study, we explored the biological functions of AMIGO2 in bladder cancer." (PMID 38978149, 2024). "Knockdown of AMIGO2 suppresses bladder cancer cell proliferation and migration." (PMID 38978149, 2024). "AMIGO2 is overexpressed in bladder cancer cells and tissues." (PMID 38978149, 2024). "Interestingly, we found that overexpression of PPAR-γ in AMIGO2-repressed cells could revert the inhibitory effect of shAMIGO2 on bladder cancer cells." (PMID 38978149, 2024). "To explore the mechanism of AMIGO2-induced cell proliferation, we investigated potential targets of AMIGO2 and found that PPAR-γ is targeted by AMIGO2 and is essential for the bio-function of bladder cancer." (PMID 38978149, 2024).
colon cancer (2 papers, 2017 to 2024). "Up-regulation of AMIGO2 is related to terminal stage of colon cancer patients." (PMID 38189855, 2024). "Increased expression of Amigo2 also correlated with poor prognosis in colon cancer patients." (PMID 28272394, 2017). "Furthermore, PrognoScan-based Kaplan-Meier survival analysis revealed a correlation between higher Amigo2 expression levels and shorter survival times in 177 colon cancer patients (p < 0.05)." (PMID 28272394, 2017).
ovarian carcinoma (2 papers, 2022 to 2024). A malignant neoplasm originating from the surface ovarian epithelium. "After knockout of AMIGO2 in ovarian cancer cells, the capacity of cell migration, invasion in vitro and metastasis in vivo is significantly compromised." (PMID 38189855, 2024).
endometriosis (1 paper, 2015). The growth of functional endometrial tissue in anatomic sites outside the uterine body. "However, little is known about the role of AMIGO2 in the development of endometriosis." (PMID 26357653, 2015).
gastric tumour (1 paper, 2022). "In this study, we performed immunostaining of primary gastric tumour tissues with the specific monoclonal antibody (rTNK1A0012a) for human AMIGO2 to investigate the relationship between AMIGO2 expression and various metastatic and clinical outcomes." (PMID 35296279, 2022).
lymph node metastasis (1 paper, 2022). "In contrast, analysis using rTNK mAb eliminated the risk of lymph node metastasis and vascular invasion, leaving only AMIGO2 expression (p = 7.930E-10) and sex (p = 0.049)." (PMID 35094710, 2022).
metastasis (1 paper, 2022). The spread or migration of cancer cells from one part of the body (where they first appeared) to another. "The frequency of liver metastasis (p = 0.006) and peritoneal dissemination (p = 0.047) was higher in the high AMIGO2 expression group than in the low expression group." (PMID 35296279, 2022).
osteosarcoma (1 paper, 2021). A usually aggressive malignant bone-forming mesenchymal neoplasm, predominantly affecting adolescents and young adults. "Expression of ABCA3, CTGF, and AMIGO2 were significantly higher in metastatic osteosarcoma samples compared to the primary osteosarcoma samples while the expression of PREB, FHIT, and EXOSC5 were significantly decreased in metastatic osteosarcoma samples." (PMID 34368151, 2021).
pancreatic adenocarcinoma (1 paper, 2026). "Together, these findings support the view that although AMIGO family members may broadly modulate tumor biology, AMIGO2 is the dominant functional driver in pancreatic adenocarcinoma, likely through adhesion-related mechanisms." (PMID 41583520, 2026).